IL1B (interleukin 1 beta)
Diseases named in the same sentence as IL1B in open-access papers (continued):
Sharing a sentence is not in itself a finding about the gene and the disease.
endometriosis (continued). "Accordingly, IL-1β levels in the peritoneal fluid of mice with endometriosis were elevated compared with the sham group and were reduced when exposed to the NLRP3 inhibitor." (PMID 34630429, 2021). "These endometriosis-like phenotypes can be reproduced in control ME-SFCs by exposure to inflammatory cytokines (TNF and IL-1β) and are associated with increased cell migration." (PMID 36304708, 2020). "Endometriosis is an inflammatory disease caused by increased TNF-α and IL-1β, which reduce the protein expression of Bax and increase Bcl-2 to inhibit the apoptosis of endometriotic lesions." (PMID 33266505, 2020). "The highest dose of IL-1β (100 pg/mL) induced significantly more proliferation of Ectopic-ES derived from ovarian endometriosis compared to that of deep infiltrating endometriosis." (PMID 32528066, 2020). "Chang used expression profiling to identify mechanisms involved in the malignant transformation of endometriosis to ovarian cancer; 18 genes were identified, including NLRP3, IL-1B, and IL-18, which implicated inflammasomes." (PMID 31923221, 2020). "IL-1β, which reportedly exhibits an excessive concentration and activity in endometriosis, is a potent pro-inflammatory cytokine synthesized by macrophages." (PMID 32145751, 2020). "IL-1β is thought to act on endometrial stromal cells and to be involved in the development of endometriosis." (PMID 31507610, 2019). "In the early development stage of endometriosis, acute inflammatory responses and tissue breakdown were induced by pro-inflammatory cytokines such as interleukin (IL)-6, IL-1β, interferon (IFN)-γ, and tumor necrosis factor (TNF)." (PMID 31636643, 2019). "IL-1β is the more studied inflammatory cytokine involved in the pathophysiology of endometriosis, with multiple roles in the disease development." (PMID 32063886, 2019). "While the immediate effect of antalarmin in inflammatory molecules was not the main objective of our current experiments, we recognize that inflammatory activity mainly via TNF-α, IL-6, IL-1β, among others has a significant role in endometriosis." (PMID 30427841, 2018). "Increased entopic endometrial mRNA levels of αV integrin and αVβ3 integrins have also been shown in women with endometriosis as compared to healthy controls, which occurs in conjunction with increased peritoneal IL-1β mRNA levels." (PMID 29772648, 2018). "In women with endometriosis, inflammatory mediators including interleukin (IL)-1β, IL-6, tumor necrosis factor (TNF)-α, prostaglandins (PGs) and nerve growth factor (NGF) have been demonstrated to be elevated in peritoneal fluid and/or endometriotic lesions." (PMID 28898282, 2017). "This idea is further supported by studies reporting impaired expression of the soluble decoy receptor IL-1-RII in the endometrium and PF of women with endometriosis, which would help attenuate the effects of IL-1α and IL-1β." (PMID 26247027, 2015). "A study by Bergqvist and colleagues found that endometriotic lesion expresses higher levels of IL-1β than eutopic endometrium of both normal women and women with endometriosis, which indicates that the inflammation in endometriosis is locally induced." (PMID 26247027, 2015). "COX-2, the rate limiting enzyme in PGE2 biosynthesis, is increased in ectopic and eutopic endometrial tissues of endometriosis patients compared to healthy controls by cytokines such as IL-1β." (PMID 24587003, 2014). "In the present study we examined the effect of LXA4 on the IL-1β-COX-2-PGE2-VEGF axis as well as on ERα and E2-regulated genes implicated in an experimental endometriosis model." (PMID 24587003, 2014). "A large body of evidence indicates that TNFα and IL1β, typical inflammatory cytokines, are involved in macrophage activation, inflammatory change, and enhanced angiogenesis to develop endometriosis." (PMID 23843796, 2013). "Dienogest reduced IL-1β production from peritoneal macrophages and implant volume in a rat model of endometriosis." (PMID 23766765, 2013).
endometriosis (continued). "MUC2 expression was reported to be regulated by many endometriosis-related cytokines, such as IL-1β, IL-6, TNF-α, NF-Kappa B." (PMID 22417007, 2012). "Interleukin (IL)-1β, a proinflammatory cytokine, is considered to play an important role in the pathogenesis of endometriosis." (PMID 21801462, 2011). "Pro-inflammatory cytokine concentrations in peritoneal fluid increase in women with endometriosis, and IL-1β is suggested to play an important role in the pathogenesis of endometriosis." (PMID 21801462, 2011). "Reportedly, stromal cells from endometriotic lesions and the endometrium in women with endometriosis show reduced decidualization capacity, and IL-1β inhibits cAMP-mediated decidualization in primary human ESCs." (PMID 21801462, 2011). "For example, in patients with endometriosis, interleukin-1β (IL-1β) is produced by activated macrophages and results in the increased expression of VEGF." (PMID 20085636, 2010). "Both conditions also exhibit dysregulation of the IL-1β/IL-1RA axis, with endometriosis patients showing increased peritoneal IL-1β41 (a potent pyrogen and pain mediator) and ME/CFS patients demonstrating elevated systemic IL-1RA, suggesting chronic but ineffective anti-inflammatory compensation." (PMID 41008704, 2025). "Overactive estrogen receptors diminish HDL function and elevate TG and NHHR, which then activate the NLRP3 inflammasome and drive excessive IL-1β release, sustaining lesion growth and underscoring the pivotal role of the lipid–inflammation axis in endometriosis." (PMID 41268163, 2025). "Serum IL-1β levels are positively correlated with estrogen, and experimental evidence has shown that IL-1β levels are substantially elevated in patients with endometriosis primarily induced by estrogen." (PMID 41332984, 2025). "The signals for IL1B eQTLs look to be independent of the endometriosis risk association and are likely a consequence of linkage disequilibrium." (PMID 40938538, 2025). "TRIM24 potentially facilitates endometriosis progression through the NLRP3/caspase-1/IL-1β pathway." (PMID 40508002, 2025). "In cases of endometriosis, however, elevated levels of cytokines in the peritoneal fluid, such as interleukin (IL)-6, IL-1β, IL-8, tumor necrosis factor (TNF)-α, and transforming growth factor (TGF)-β, contribute to the development of a chronically inflamed peritoneal environment." (PMID 40692689, 2025). "All endometriosis forms share core immunopathogenetic mechanisms: macrophage accumulation with M2 polarization, reduced NK cytotoxicity, elevated pro-inflammatory cytokines (IL-1β, IL-6, TNF-α) alongside immunosuppressive mediators (IL-10, TGF-β)." (PMID 41488658, 2025). "Endometriosis risk variants in the chromosome 2q14.1 locus were mapped to eQTLs to identify evidence that genetically regulated expression differences in IL1A and/or IL1B are conferred by the same variants associated with endometriosis risk." (PMID 40938538, 2025). "There are many studies on IL1 in endometriosis, especially on IL1β, but very few on IL1α." (PMID 41154663, 2025). "Patients diagnosed with endometriosis demonstrated significantly heightened levels of inflammatory cytokines, specifically interleukin-1 beta (IL-1β), interleukin-6 (IL-6), interleukin-8 (IL-8), vascular endothelial growth factor, CCL2, CCL5, and tumor necrosis factor-alpha (TNF-α)." (PMID 40303639, 2025). "Notably, even the second unaffected ovary from endometriosis patients exhibited mild levels of IL-1β." (PMID 38732021, 2024). "While abundant cytokines and chemokines have been observed in the pelvic cavity of endometriosis patients, TNFα, IL-1β, and IL-6 are considered the key factors involved in maintaining the aberrant peritoneal inflammatory environment, promoting lesion growth, and mediating peripheral sensitization." (PMID 39192982, 2024). "The NLRP3/IL-1β pathway plays a role in endometriosis development, and NLRP3 inhibitors may help reduce ovarian endometrioma size and improve ovarian function." (PMID 40034240, 2024).
endometriosis (continued). "NLRP3, IL-1β, and IL-18 are upregulated during transformation of endometriosis to ovarian cancer." (PMID 39769450, 2024). "Moreover, IL-1β enhances IL-6 and IL-8 production; they act synergistically to boost proliferation and decrease the apoptotic rate of endometriosis cells." (PMID 37447296, 2023). "Hence, inflammatory mediators such as IL‐1β, IL‐6, IL‐8 increase in the peritoneal, serum, and endometrium of endometriosis patients, leading to enhancing proliferation and decreasing apoptotic rate in endometriotic cells." (PMID 36266431, 2022). "We hypothesized that inhibiting NLRP3 with MCC950 would suppress interleukin-1 beta (IL-1β) and alleviate endometriosis." (PMID 35351143, 2022). "The findings of this study suggest that DNG may reduce cell viability and proliferation in response to treatment with estrogen, TNF-α, IL-1β, or IL-32, and inhibit the pathogenesis of endometriosis by decreasing PCNA expression." (PMID 36428561, 2022). "We demonstrated that endometriosis lesions exhibited higher expression of IL-1β than eutopic endometrium, corroborating our hypothesis of upregulated senescence marker expression in endometriosis lesions." (PMID 35269619, 2022). "Finally, the M1 pro-inflammatory cytokines TNF-α and IL-1β were identified as promising targets in the treatment of endometriosis." (PMID 36555618, 2022). "IL-1b is a major proinflammatory cytokine released in excess by endometriosis-derived peritoneal macrophages and found in high levels in the peritoneal fluid of endometriosis patients." (PMID 35059465, 2022). "Besides, significant downregulation (p < 0.05) of the level of IL-1β was shown in the culture of endometriosis cells with genistein as compared with control group for 6, 24 and 48 h incubation period (20–50 μM, 5–50 μM and 10–50 μM respectively)." (PMID 35140617, 2022). "Few studies have linked IL-1β secretion with the induction of IL-17-producing cells, and thus the relationship between IL-1β and endometriosis may be related to IL-17 production." (PMID 35269619, 2022). "Proinflammatory factors, cytokines and interleukin 1 beta (IL-1β) may disrupt PR function and contribute to progesterone resistance, ultimately resulting in increased nuclear factor kappa B (NFκB) involvement in endometriosis development." (PMID 36359004, 2022). "The present study demonstrated that in the same patient, the retrocervical deep-endometriosis lesion has pro-senescence characteristics, as shown by the presence of higher IL-1β and p16Ink4a expression and lower lamin b1 expression, compared to the eutopic endometrium." (PMID 35269619, 2022). "Endometriosis patients also display increased IL-1β, IL-6, and TNFα." (PMID 36532015, 2022). "However, this action contributes to the inflammatory profile observed in patients with endometriosis through the secretion of IL-6 and IL-1β by these cells." (PMID 35807280, 2022). "Numerous mechanisms are involved in endometriosis-related pain such as various algogens (pain-producing agents), cytokines (such as IL-1b, IL-6, and TNF-a), growth factors (such as b-nerve growth factor and vascular endothelial growth factor), and several chemokines, such as CCL243,44." (PMID 36266431, 2022). "Also, overexpression of MCP-1 (CCL2) and IL-1β in endometrium of women with endometriosis suggests increased infiltration of monocytes that differentiate to macrophages in this tissue in women with disease." (PMID 35421980, 2022). "Our results indicate that the exposure of MCs to estrogen stably drives NLRP3 expression critical for caspase-1 activation and IL-1β secretion, which might contribute to the local proinflammatory environment in endometriosis." (PMID 34630429, 2021). "It has been suggested that the imbalanced state of IL-1β and its decoy inhibitory receptors may contribute to infertility in patients with endometriosis." (PMID 33906696, 2021).
endometriosis (continued). "Our in vivo data supported that NLRP3 inhibitor CY-09 could suppress IL-1β production in MCs and protect against lesion development and fibrosis in endometriosis." (PMID 34630429, 2021). "We found that treatment with the inflammatory cytokine, interleukin-1β (IL-1β) induced WEE1 expression in ESCs, indicating that upregulation of WEE1 may be associated with the inflammatory response during endometriosis." (PMID 34686198, 2021). "Notably, recent concepts depicting the therapeutic role of IL-1β in endometriosis have emerged, raising the question of which one is the better treatment strategy, targeting IL-1β or NLRP3, or even a combined regimen." (PMID 34630429, 2021). "The role of IL-1β and IL-2 in the endometriosis development is still unclear." (PMID 34639133, 2021). "Additionally, the authors showed the changes that were induced by IL-1β on the morphology of eutopic endometriosis stromal cell (EESC) and its effect on RANTES secretion via the IL-1 receptor." (PMID 33435569, 2021). "Several authors have shown, for example, an increase in the cytokine IL-1β in patients with endometriosis and they correlate this increase with the activation of inflammasomes by stimulating microorganisms, and also correlate the participation of this event in the pathogenesis of the disease." (PMID 32192080, 2020). "This inhibitor may provide a powerful therapeutic agent capable of suppressing the augmentation of endometriosis induced by IL-1β, IL-33, and LPS." (PMID 31507610, 2019). "Our present work detected IL-1β in ascites and serum, and considering the involvement of inflammasomes, IL-1β may have an important role in endometriosis." (PMID 31507610, 2019). "It is suggested that endometriosis pain induced by inflammatory mediators such as IL-1β may be through ERK signal pathway." (PMID 28898282, 2017). "Various studies have reported higher concentrations of IL-1α, IL-1β, and total IL-1 in the PF of women with endometriosis compared to normal women, thus supporting the notion of a local inflammatory environment in endometriosis." (PMID 26247027, 2015). "Both HIFa and NFκB can be activated by elevated levels of IL-1β and TNFα in endometriosis." (PMID 24927773, 2014). "On the other hand, patients with the variant allele of rs1434536 could maintain relatively unaffected levels of BMPR1B, CA125, and IL-1β, offsetting elevation of miR-125b level presented in endometrium cells, which may prevent endometriosis." (PMID 24339876, 2013). "Although DCs do not directly contribute to the pain associated with endometriosis, they may do so indirectly by secreting cytokines that support lesion survival, such as IL-10, and pro-inflammatory cytokines like IL-1β and IL-6, which promote neurogenesis." (PMID 40747182, 2025). "Moreover, endometriotic lesions exhibit higher levels of IL-1β expression compared to both eutopic endometria from healthy women and those with endometriosis, underscoring the locally induced inflammation characteristic of endometriosis." (PMID 38928175, 2024). "Moreover, uric acid may be involved in the development of endometriosis through interleukin-1β (IL-1β)." (PMID 37138241, 2023). "New lymphatic vessels may serve as a channel for the infiltration of immune cells into the endometriotic microenvironment; these immune cells further produce the proinflammatory cytokine IL-1β, which in turn further activates the NF‐κB pathway to promote lymphangiogenesis in endometriosis." (PMID 37143676, 2023). "The interaction between ER-β and the inflammasome machinery increases IL-1β levels and inhibits TNFα-induced apoptosis, resulting in immune escape, the survival of ESCs, and the epithelial-mesenchymal transition pathway, which plays an essential role in the pathogenesis of endometriosis." (PMID 36865552, 2023). "Additionally, TNF-α and IL-1β affect nuclear signaling, which may contribute to the pathogenesis of endometriosis." (PMID 36428561, 2022).
endometriosis (continued). "Indeed, the NLRP3 inflammasome induces caspase-1 and IL-1β in endometriosis." (PMID 36093086, 2022). "The NLRP3 level was significantly higher than that of other NLRs in OE samples and CSCs; therefore, the specific inhibition of NLRP3 by MCC950 could suppress IL-1β production in endometriosis, while essential responses against bacterial infections may remain intact." (PMID 35351143, 2022). "Thus, DNG may reduce cell viability and proliferation induced by estradiol, TNF-α, IL-1β, and IL-32, and inhibit the endometriosis pathogenesis by decreasing PCNA expression." (PMID 36428561, 2022). "It has been reported that the nucleotide-binding oligomerization domain, leucine-rich repeat, and pyrin domain-containing (NLRP) 3 inflammasome, which contributes to the activation of interleukin-1 beta (IL-1β), might be related to the progression of endometriosis." (PMID 35351143, 2022). "Proinflammatory cytokines such as TNF-α, IL-1β, IL-6, and IFN-γ initiate and amplify inflammatory and immune responses by signaling the recruitment of additional proinflammatory mediators and immune cells to the site of injury and have been implicated in endometriosis development and progression." (PMID 35409294, 2022). "In addition, we investigated whether treatment of control ME-SFCs with inflammatory cytokines (TNF and IL-1β) could induce an endometriosis-like phenotype." (PMID 36304708, 2020). "The target cells of LPS are unknown for endometriosis, but considering LPS acts on cells such as macrophages to produce IL-1β, it is possible that exacerbation of endometriosis by LPS may be mediated by induction of IL-1β." (PMID 31507610, 2019). "Interestingly, COX2 is differentially regulated in ectopic and eutopic endometrium from endometriosis patients in response to IL-1β, since ectopic tissue is more sensible to this induction that is important to sustain inflammatory microenvironment that in turn sustain lesion development." (PMID 32063886, 2019). "Moreover, invalid IL-1β and IL-18 maturation by interleukin-1 converting enzyme (ICE) may be an important pathogenic factor in endometriosis." (PMID 23843796, 2013). "Additionally, IL-1β is recognized for its role in amplifying the inflammatory response by upregulating MMP12, MMP1, PAI2, and other cytokines and growth factors, thereby fostering neovascularization as well as matrix remodeling, which are implicated in the development of endometriosis." (PMID 40303639, 2025). "Research has also highlighted proangiogenic factors, such as VEGF, IL-1β, and TNF-α, which play a crucial role in the vascularization of endometriosis." (PMID 40508002, 2025). "In endometriosis, for example, an excess of pro-inflammatory cytokines like TNF-α, IL-1β, and IL-6 leads to chronic inflammation and the formation of lesions outside the uterus, this can impair fertility." (PMID 41377340, 2025). "At the systemic level in patient blood, elevated levels of IL-1β and soluble TNF receptor type 2 (sTNFR2) are frequently recorded, with the latter considered a potential early marker of endometriosis development." (PMID 41488658, 2025). "Monocytes in women with endometriosis tend to produce higher levels of pro-inflammatory cytokines such as TNF-α, IL-1β, and IL-6." (PMID 41377340, 2025). "Research has shown increased levels of IL-1β, IL-6, and TNF-α in tissues affected by endometriosis, which confirms the crucial role of these cytokines in the disease’s pathophysiology." (PMID 40725782, 2025). "Granulosa cells from women with endometriosis show elevated levels of the NLRP3 inflammasome and increased IL-1β and IL-18 in follicular fluid, contributing to infertility." (PMID 40508002, 2025). "Moreover, IL-1β and IL-6 could be used as predictors for endometriosis." (PMID 39859551, 2025). "There was also a tendency for eutopic endometrium from endometriosis cases to express higher IL1R1 and lower IL1A and IL1B." (PMID 40938538, 2025).